IFT25 (intraflagellar transport 25)
Description:
Component of the IFT complex B required for sonic hedgehog/SHH signaling. May mediate transport of SHH components: required for the export of SMO and PTCH1 receptors out of the cilium and the accumulation of GLI2 at the ciliary tip in response to activation of the SHH pathway, suggesting it is involved in the dynamic transport of SHH signaling molecules within the cilium. Not required for ciliary assembly. Its role in intraflagellar transport is mainly seen in tissues rich in ciliated cells such as kidney and testis. Essential for male fertility, spermiogenesis and sperm flagella formation. Plays a role in the early development of the kidney. May be involved in the regulation of ureteric bud initiation (By similarity).
Synonyms: Hspb11; PP25; C1orf41; HSPCO34; FAP232; CFAP232
Tractability: PROTAC: ubiquitination databases record sites on it.
Gene: Protein-coding gene on chromosome 1 (53,916,574 to 53,946,588, reverse strand). Ensembl gene ENSG00000081870.
Subcellular location: Cell projection, cilium
Subcellular location (Human Protein Atlas): End piece; Mid piece; Principal piece
Pathways (Reactome):
Organelle biogenesis and maintenance: Intraflagellar transport
Gene Ontology:
Molecular function: protein binding
Biological process: cilium assembly; intraciliary anterograde transport; kidney development; smoothened signaling pathway; spermatogenesis; intraciliary transport
Cellular component: intraciliary transport particle A; intraciliary transport particle B; centrosome; ciliary tip; cilium; intraciliary transport particle
Genetic constraint (gnomAD): Loss-of-function variants: 1 observed, 4.42 expected, observed/expected ratio (o/e) 0.23, 90% interval 0.079 to 1.07. That is too few expected variants to judge how well the gene tolerates losing a copy. Missense variants: 33 observed, 40.8 expected, observed/expected ratio (o/e) 0.81, 90% interval 0.61 to 1.08. Synonymous variants: 16 observed, 10.25 expected, observed/expected ratio (o/e) 1.56, 90% interval 1.03 to 1.94.
Homologues: Orthologues: pig IFT25 (90% identical), dog YIPF1 (90% identical), mouse Ift25 (85% identical), rat Ift25 (85% identical), chimpanzee IFT25 (82% identical), guinea pig IFT25 (81% identical), macaque IFT25 (73% identical), tropical clawed frog ift25 (54% identical).
Diseases named in the same sentence as IFT25 in open-access papers:
IFT25 is named in the same sentence as 8 diseases in open-access papers, as found by Europe PMC text mining. Sharing a sentence is not in itself a finding about the gene and the disease. The quoted sentences say what the papers report.
Infertility (1 paper, 2025). "We reported that disruption of Ift20, Ift25, and Ift27 in male germ cells resulted in infertility." (PMID 40348912, 2025). "Likewise, IFT81 male mice were infertile associated with reduced IFT-B components in testes, and others, including IFT20, IFT25, IFT27, IFT57, IFT74, and IFT88, but there was no change in the IFT-A complex protein IFT140." (PMID 40348912, 2025).
IFT25 also shares sentences with these, for which no sentence is quoted: ciliopathy (1 paper); COVID-19 (1); depression (1); glioma (1); renal agenesis (1); renal hypoplasia (1); tumours (1).